MTOR (mechanistic target of rapamycin kinase)
Diseases named in the same sentence as MTOR in open-access papers (continued):
Sharing a sentence is not in itself a finding about the gene and the disease.
tumor (continued). "Hypoxia-induced tumor exosomes containing let-7a microRNA (miRNA) enhance mitochondrial OXPHOS activity and suppress insulin/Akt/mTOR signaling pathway in bone marrow-derived macrophages (BMMs), as a result, promotes polarization of infiltrating macrophages to an M2-like phenotype." (PMID 35250965, 2021). "While tumor grade has no impact on prognosis in this investigation, the detrimental influence of mTOR activation on DSS turns out to be apparent in the multivariate analysis." (PMID 34066040, 2021). "Here, we showed that DHA inhibited mTORC1 in tumor cells not through direct binding to mTOR or FKBP12, but via indirect mechanisms." (PMID 34205996, 2021). "In conclusion, JIB extract combined with cisplatin had synergistic effects on the suppression of tumor cell growth and induction of apoptosis in B16/F10 cells through different molecular pathways, including AKT/mTOR, MAPK pathways, cell cycle arrest and caspase-dependent pathways." (PMID 33390784, 2021). "Conversely, mTOR-specific inhibitors eliminated the effects of NRBP2 knockdown on increasing cell proliferation, invasion and the EMT, which suggested the anti-tumor effect of NRBP2, which may be partially related to the regulation of the AMPK/mTOR pathway." (PMID 33816275, 2021). "Other reported findings impart evidence that NOTCH1 and DLL4 were overexpressed within the tumor vasculature and upregulation of NOTCH/c-MYC activates the AKT pathway via PTEN phosphorylation; consequently, the NOTCH activation intensifies PI3K/mTOR activity." (PMID 34940041, 2021). "Since mTOR activation is associated with resistance to chemotherapy agents, in vitro CRP identified efficacious cytotoxic anticancer agents to which the tumor had not acquired resistance despite mTOR activation." (PMID 33935721, 2021). "TKIs target enzymes that are responsible for the activation of several intracellular molecular pathways often involved in tumor cell proliferation, such as phosphatidylinositol 3-kinase (PI3K), thymoma viral proto-oncogene (AKT), and mammalian target of rapamycin (mTOR)." (PMID 33337518, 2021). "The adaptation and survival of tumor cells in heterogeneous microenvironments requires the coordination of complex pathways and mechanisms, such as hypoxia induction factor 1 (HIF-1), unfolded protein reaction (UPR), rapamycin (mTOR), and autophagy." (PMID 34465721, 2021). "PI3K/Akt/mTOR axis can sense and integrate inputs from a variety of environmental signals in the context of TME to regulate the immune cell trafficking, polarization, and their functional properties to promote tumor progression and metastasis." (PMID 35250965, 2021). "CSNK1G2 selectively manipulates the tumor progress, sometimes in a nuclear and genomic manner via ERE inhibition of specific genes associated with tumor growth, but sometimes by non-genomic manner via the AKT/mTOR/S6K pathway, followed by p-ER167 activity." (PMID 33861751, 2021). "Recent examples include knockdown of ACLY impairing pancreatic tumor formation and knockdown of FASN blocking tumor development in mTOR-driven liver cancer, while pharmacological inhibition of FAS reduced tumor growth in preclinical models of castration-resistant prostate cancer." (PMID 33413672, 2021). "Mechanically, BO regulated the host’s amino acid profile via the metabolism alternation of the gut microbiota, and then mTOR was activated in an amino acid–regulated form to restrain the hyper-autophagy within the MDA-MB-231 tumor, resulting in a distinct tumor suppression." (PMID 34658867, 2021). "Induction of p27kip1 tumor suppressor gene accumulation by attenuating p27kip1 at Thr 187 phosphorylation; inhibition of CDK2 activation through binding with the CDK2 complex; inhibition of mTOR kinase activity by binding with the mTOR complex." (PMID 34630112, 2021).
tumor (continued). "Indeed, glucose consumption by tumors and macrophages metabolically impairs T cells, leading to their reduced mTOR activity, glycolytic capacity and IFN-γ production, thereby allowing tumor progression." (PMID 33802061, 2021). "Notably, therapeutic inhibition of mTOR with rapamycin or temsirolimus induced preferential apoptosis of CSC, when compared to bulk tumor cells." (PMID 33479203, 2021). "These signalling aberrations emerge in post-treatment tumour biopsies and are attributed to resistance to all TKI generations via activation of mitogen-activated protein kinase kinase (MEK)/extracellular signal regulated kinase (ERK), and Akt/mTOR pathways." (PMID 34069119, 2021). "Upon the negative changes in the microenvironment, tumor cells initiate the adaptation process and activate various signaling cascades like mTOR, NF-KB, AKT." (PMID 33597817, 2021). "To date, clinical tumor biomarkers that accurately predict or monitor tumor response to PI3K/Akt/mTOR targeted drugs are not available." (PMID 34113218, 2021). "Previous studies have found that drugs can activate the PI3K/AKT/mTOR and DNA damage repair pathways, and the combined application of PKI-587 can inhibit the activation of these two pathways, thereby enhancing the sensitivity of tumor cells to drugs." (PMID 34665844, 2021). "Our results showed that mTOR signaling pathway could be activated by CD36 in HCC and inhibition of mTOR eliminates CD36-mediated glycolysis and tumor-promoting effects." (PMID 33771982, 2021). "It is reported that the EGFR/PI3K/Akt/mTOR signaling pathway and inhibition of STAT3 may be the imperative mechanisms mediating oxymatrine-regulated anti-tumor action of GBM cells." (PMID 33768139, 2021). "Our data show deregulation of inositol metabolism and RTKs in MB cells and G4 tumour samples with a BMI1High;CHD7Low signature and activation of the mTOR signalling pathway in these cells, but not in hNSC with the same molecular signature." (PMID 33846320, 2021). "Finally, mice model experiments confirm BI853520 treatment dramatically reduces tumor growth in vivo and suppresses the activation of PI3K/AKT/mTOR signal pathway." (PMID 35201437, 2021). "mTOR also drives components of the translational machinery S6K, 4EBP-1, and sterol regulatory element-binding protein (SERBP)-1, that support cell proliferation and lipid metabolism in tumor cells." (PMID 33920158, 2021). "In addition, MDK can activate the Akt signalling pathway in tumour and endothelial cells and promote VEGFR3 expression through mTOR signalling pathway to promote tumorigenesis and development." (PMID 34759262, 2021). "Furthermore, immunofluorescence staining assay was performed to detect activated p-AKT and p-mTOR in mice tumor slides, results showed that BI853520 treatment group had lower level of p-AKT and p-mTOR compared to normal control." (PMID 35201437, 2021). "mTOR, a downstream player of the PI3K/AKT signaling pathway, regulates tumor cellular functions." (PMID 34922551, 2021). "The few comparisons we did perform within our cohort (e.g., tumor growth rate in patients on mTOR inhibitors and those without) were exploratory in nature, and are presented as such." (PMID 33897589, 2021). "PI3K-AKT/mTOR pathway is downregulated by PTEN, a tumor suppressor." (PMID 33807612, 2021). "The study aimed at assessing whether curcumin induces apoptosis of RCC and the involvement of AKT/mTOR pathway, the effects of curcumin on TNF-α, IL-6 and IL-8 cytokines, and finally, to understand the role of curcumin in autophagy and tumor-growth in vivo." (PMID 34402718, 2021). "Considering the close connection between puerarin and the mTOR pathway, our research results indicate that puerarin may regulate downstream GLUT1 through the mTOR pathway and affect tumor cell metabolism." (PMID 34863080, 2021). "The mTOR inhibitor in combination with anti-PD-1 therapy did indeed maintain allograft tolerance without compromising anti-tumor efficacy." (PMID 34899357, 2021).
tumor (continued). "In addition, digoxin inhibited the phosphorylation of Akt, mTOR and p70S6K, signaling molecules of the PI3K/Akt pathway that are known to be involved in tumor cell survival, proliferation, metastasis and autophagy." (PMID 34549269, 2021). "When tested in DR5‐treated tumor cell‐jurkat cell co‐culture reporter assays, inhibition of various posttranslational PD‐L1 stability regulators such as mTOR, STAT3, CDK1, and NF‐kβ did not change PD‐L1 surface expression." (PMID 33587338, 2021). "HSPD1 encodes a member of the heat shock protein 60 gene family, could improve the survival rates of tumor cells through the endogenous apoptotic pathway, and promotes tumor cell proliferation via the ROS/AMPK/mTOR pathway." (PMID 33681194, 2021). "However, inhibition of one pathway alone will often result in minor to moderate anti-tumor activity, suggesting concurrent targeting of MYCN transcription and mTOR signaling is important strategy to enhance efficacy." (PMID 34565342, 2021). "Furthermore, mTOR is a key kinase downstream of PI3K-Akt, which regulates tumor cell proliferation, growth, survival and angiogenesis." (PMID 32210799, 2020). "This includes mTOR, atypical PKC (aPKC)-RhoGDI, Rab11 family interacting protein 1 (Rab11-FIP1), and phosphatidylinositol-4-phosphate 5-kinase (PIP5K) signaling which can lead to fibrosis formation or tumor cell invasion and migration." (PMID 32477950, 2020). "Furthermore, the dipeptidyl peptidase (DPP)-4 inhibitor, KR62436, promoted primary tumor growth, and lung metastasis via induction of the CXCL12/CXCR4/mTOR/EMT signaling axis in a syngeneic mouse model." (PMID 32245205, 2020). "AMLs do not disappear with the use of mTOR inhibitors, since tumor regrowth is observed with withdrawal, and the effects on aneurysm reduction have yet to be clarified." (PMID 33219488, 2020). "Preclinical data on Lewis lung carcinoma mouse models demonstrated a synergic effect by the combination of anti-PD-1 and endostar (a recombinant humanized endostatin, anti-angiogenic molecule) in suppressing tumor growth by means of improving the TME and activating PI3K/AKT/mTOR-mediated autophagy." (PMID 33114576, 2020). "Moreover, as AMPK/mTOR signaling affects tumor invasion and metastasis, the AMPK downstream effectors of mTOR, p70S6K, and 4E-BP1 were also examined." (PMID 32719745, 2020). "Based on our findings, it is possible that co-administration of inhibitors of MEK, PI3K, mTOR, IDH1, EZH2 or CDK4/6 (to target CDKN2A deletion) may have been effective in slowing or reducing tumour progression." (PMID 33053751, 2020). "Indeed, combined treatment with mTOR and HDAC (Histone DeACetylases) inhibitors proved to kill NF1-mutant tumours of the nervous system both in vivo and in vitro." (PMID 33066259, 2020). "The mTOR‐dependent regulation of STAT3 and NF‐κB activity promotes an immunosuppressed phenotype in TAM‐MG, which hinders effector T‐cell proliferation and immune reactivity and contributes to tumour immune evasion." (PMID 32567735, 2020). "In conclusion, the data reported here provided strong support to the concept that reduced or silenced expression of FGF14 is modulated by DNA methylation of this gene, and FGF14 functions as a novel tumor suppressor, which induces cell apoptosis via inhibiting PI3K/AKT/mTOR signaling." (PMID 31949485, 2020). "Nevertheless, they also observed that rapamycin-mediated tumour growth inhibition was not accomplished via the generally assumed mechanisms and therefore did not induce apoptosis as expected by inhibition of the mTOR pathway." (PMID 32102484, 2020). "Average p-values across Calu6, Calu3, H358 and RH2 tumours show enrichment for genes residing in the EGF, NF-κβ, TGF-β, mTOR/PI3K/AKT, integrin, ATM and G1/S checkpoint signalling pathways that was generally greater in tumours exposed to dry powder than aqueous 5AZA." (PMID 32103148, 2020).
tumor (continued). "Non-thermal plasma exerts anti-tumor effect by inducing RNF126 mediated K48-linked polyubiquitination and degradation of mTOR." (PMID 33004065, 2020). "This suggests that local ablation therapies are not able to completely suppress mTOR pathway activity, thus explaining why tumor recurrence is almost universal if no other therapy is implemented afterwards." (PMID 32070029, 2020). "As reported, AA and its downstream metabolite prostaglandin E2 (PGE2) could modulate tumor microenvironment, and promote carcinogenesis and angiogenesis by activating PI3K-AKT signaling and mTOR signaling." (PMID 32332698, 2020). "These genetic hallmarkers make AGS and KATO III cell lines good in vitro models for the evaluation of the effects of the two drugs on cell growth and motility, on the reversal of the EMT and on the main factors involved in PI3K/Akt/mTOR and MAPK pathways that lead to tumor growth and progression." (PMID 32346056, 2020). "Similarly, amiodarone, an mTOR-independent autophagy enhancer, reduced CD133+ cell viability and tumor spheroid formation in vitro and exhibited anti-tumor activity in vivo." (PMID 32793494, 2020). "The expression of FADS1, AKT, mTOR, and S6K1 in tumor tissues was also determined by western blot and IHC, which was basically in accordance with the results in vitro that FADS1 increase the phosphorylation level of AKT, mTOR, and S6K1." (PMID 32332698, 2020). "By attaching to a specific binding site on PTEN 3′UTR luciferase reporter, miR-718 decreased PTEN’s tumor suppressor activity in a dose-dependent manner, thus activating the AKT/mTOR signaling pathway and therefore promoting cell proliferation and angiogenesis." (PMID 32211411, 2020). "Genetic analysis of the tumor sample from the best responding patient did not yield functionally relevant SNVs in genes involved in PI3K/AKT/mTOR signalling cascade." (PMID 32993794, 2020). "FADS1 overexpression could promote LSCC tumor growth and metastasis both in vitro and in vivo by activating AKT/mTOR signaling pathway." (PMID 32332698, 2020). "Noteworthy, a subanalysis of patients who had undergone locoregional ablation of the tumor prior to liver transplantation revealed a significant reduction in mTOR activity within the tumor but not in the surrounding tissue." (PMID 32070029, 2020). "It was found that in GC the signaling pathways PI3K/AKT/mTOR, RAS/RAF/ERK/MAPK, and NF-kB can jointly participate in the regulation of a number of cellular processes and suppress the sensitivity of tumor cells to chemotherapy drugs—5-fluorouracil and cisplatin." (PMID 33142817, 2020). "Cluster 2 promotes tumour growth by activating MAPK and/or mTOR signalling pathways." (PMID 32252631, 2020). "mTOR negatively regulates GAS5 expression, which induces tumor cell proliferation." (PMID 32413995, 2020). "PI3K pathway inhibitors did not decrease tumor growth in the two AKT1-mutated models, but HBCx-2 PDX responded to the mTOR inhibitor AZD2014 (TGI=86%, p=0.0001) and the dual inhibitor (mTOR and PIK3Ca) (TGI =70%, p=0.001)." (PMID 32042320, 2020). "This suggests that combinations of mTOR inhibitors and GEM might be effective combination in treatment of such tumours, especially in cases of hormone-insensivity." (PMID 33173419, 2020). "To validate in a human in vitro setting that this phenotype is microglia‐specific and not observed in peripheral macrophages, we analysed mTOR signalling in tumour‐conditioned peripheral blood monocytes/macrophages, obtained from healthy donor." (PMID 32567735, 2020).
tumor (continued). "AMPK suppresses tumor survival through inhibition of mTOR by increasing the expression of p-TSC2, a tumor suppressor gene, and leads to the inactivation of AKT and lipopolysaccharide (LPS)-induced IL-6/JAK2/STAT3 signaling in triple-negative breast cancer (TNBC)." (PMID 31952344, 2020). "As reported, single-agent therapy with BH3 mimetics caused tumor cell resistance to treatment by up-regulation of non-targeted anti-apoptotic proteins and increased activation of PI3K/AKT/mTOR pathway, providing a rationale for a combinatorial therapy." (PMID 33362794, 2020). "In this study, we found PI3K, Akt, and mTOR signaling alterations, which indicate that also LCT deregulation of these pathways may be an important event accompanying tumor development." (PMID 32180008, 2020). "They showed that NDI1 expression blocked metformin’s ability to inhibit mitochondrial complex 1, activated AMPK, and reduced mTOR pathway signaling, resulting in a lack of effective inhibition of tumor development." (PMID 31952173, 2020). "The intracellular proteins PI3K, Akt and mTOR are part of a central signaling pathway in NMTC tumorigenesis by facilitating signal transduction to induce angiogenesis, metabolic reprogramming, proliferation and invasion of tumor cells." (PMID 33112820, 2020). "The authors of several studies reported that ST8SIA1 could promote tumor growth, metastasis, and chemoresistance through the FAK/Akt/mTOR and Wnt/β-catenin signaling pathways in TNBC cell lines." (PMID 33260650, 2020). "Specifically, miR-7 reduces tumor cell proliferation and migration through PI3K/AKT/mTOR signaling." (PMID 32585931, 2020). "In addition, PRMT5 affects BUC tumor progression by distorting the Rb and p27 proteins involved in the cell cycle and facilitating the PI3K/Akt/mTOR signaling pathway." (PMID 32392182, 2020). "Moreover, elevated expression levels of phosphorylated Akt, mTOR, P70S6K, and 4E-BP1 were also observed in SPC-A1-miR-410 tumor tissues." (PMID 32528035, 2020). "Despite having no increase in tumour mass, leucine supplementation stimulated the mTOR expression in Walker-256 tumours tissue, without additional growth." (PMID 32668598, 2020). "Additional measurement of the tumour size by MRI at the beginning and at the end of the treatment period confirmed that the experimental MPNST tumours did not respond to the AKT/mTOR therapy in vivo." (PMID 32102484, 2020). "In the backdrop of Apc deletion, removal of the tumor suppressive function of TGFβ/SMAD (through Smad4 deletion) and installation of the tumor promoting function of PI3K/AKT/mTOR (through Pten deletion) independently promotes the formation of SCC of the mouse penis." (PMID 32358507, 2020). "Furthermore, CCT020312 inhibited tumor growth in an MDA-MB-453 orthotopic xenograft mouse model by activating the PERK/eIF2α/ATF4/CHOP pathway and inhibiting the AKT/mTOR pathway." (PMID 32508655, 2020). "We further demonstrated that FGF14 might act as a tumor suppressor which inhibited cell growth and induced cell apoptosis of CRC through mediating PI3K/AKT/mTOR signaling pathway." (PMID 31949485, 2020). "In a prospective study including 49 patients with HCC who underwent liver transplantation, the explanted liver was analyzed to determine the mTOR pathway expression both in the tumor and in the surrounding non-tumoral cirrhotic tissue." (PMID 32070029, 2020). "Moreover, they also confirmed that the down-regulation of LRRK2 in cultured tumor cells compromises MET activation and selectively reduces downstream MET signaling to mTOR and STAT3." (PMID 32196072, 2020).